DNAJB13 (DnaJ heat shock protein family (Hsp40) member B13)
Description:
Functions as part of axonemal radial spoke complexes that play an important part in the motility of sperm and cilia.
Synonyms: TSARG6; RSPH16A; CILD34; TSARG5
Tractability: Small molecule: a structure with a bound ligand is known.
Gene: Protein-coding gene on chromosome 11 (73,951,014 to 73,970,366, forward strand). Ensembl gene ENSG00000187726.
Subcellular location: Cell projection, cilium, flagellum
Subcellular location (Human Protein Atlas): End piece; Mid piece; Plasma membrane; Principal piece; Mitotic chromosome; Nucleoli; Nucleoli rim; Primary cilium; Primary cilium tip; Vesicles
Gene Ontology:
Molecular function: protein binding; protein-folding chaperone binding
Biological process: axonemal central apparatus assembly; cilium movement; flagellated sperm motility; protein folding; microtubule-based process
Cellular component: motile cilium; sperm end piece; sperm flagellum; sperm midpiece; sperm principal piece; 9+2 motile cilium; axoneme; cilium; cytosol; radial spoke; sperm head-tail coupling apparatus; cytoplasm
Genetic constraint (gnomAD): Loss-of-function variants: 19 observed, 30.99 expected, observed/expected ratio (o/e) 0.61, 90% interval 0.43 to 0.9. The upper end of that interval is the gene's LOEUF score, 0.9, which puts it in group 3 of 6, group 1 being the genes least tolerant of losing a copy. Missense variants: 319 observed, 336.67 expected, observed/expected ratio (o/e) 0.95, 90% interval 0.86 to 1.04. Synonymous variants: 112 observed, 127.51 expected, observed/expected ratio (o/e) 0.88, 90% interval 0.75 to 1.03.
Gene-disease validity (ClinGen):
ClinGen rates the evidence that DNAJB13 causes each of these diseases.
primary ciliary dyskinesia 34 (autosomal recessive): Moderate.
Homologues: Orthologues: chimpanzee DNAJB13 (99% identical), dog DNAJB13 (94% identical), macaque DNAJB13 (92% identical), pig DNAJB13 (92% identical), guinea pig DNAJB13 (91% identical), mouse Dnajb13 (89% identical), rabbit DNAJB13 (89% identical), tropical clawed frog dnajb13 (71% identical), rat Dnajb13 (64% identical), zebrafish dnajb13 (61% identical), Drosophila melanogaster CG12020 (35% identical). Paralogues in human: DNAJB1 (52% identical), DNAJB5 (50% identical), DNAJB4 (48% identical), DNAJB11 (30% identical), DNAJB6 (26% identical), DNAJB7 (23% identical), DNAJB12 (22% identical), DNAJB2 (22% identical), DNAJB8 (20% identical), DNAJB14 (19% identical), DNAJB9 (17% identical).
Diseases named in the same sentence as DNAJB13 in open-access papers:
DNAJB13 is named in the same sentence as 16 diseases in open-access papers, as found by Europe PMC text mining. Sharing a sentence is not in itself a finding about the gene and the disease. The quoted sentences say what the papers report.
male infertility (5 papers, 2018 to 2025). The inability of the male to effect fertilization of an ovum after a specified period of unprotected intercourse. "More importantly, mutations in DNAJB13 cause severe oligo-astheno-teratozoospermia and male infertility in humans." (PMID 37004113, 2023). "Remarkably, the transcripts encoding genes such as ZMYND15, KLHL10, TDRD1, TSSK2 and DNAJB13, which are linked to male infertility in other species, were differentially expressed among the treatments." (PMID 30697164, 2018). "Importantly, it has been reported that homozygous mutations in DNAJB13, a radial spoke protein of the mouse ‘9+2’ axoneme that localized to the sperm flagella, cause male infertility, with severe oligo-astheno-teratozoospermia." (PMID 33391882, 2020). "While the small effect size of some variants warrants validation in larger cohorts, this body of work reinforces DNAJB13 as a compelling candidate gene and suggests that rare or low-frequency variants within HSP40 family members are key contributors to the complex etiology of male infertility." (PMID 41413469, 2025).
primary ciliary dyskinesia (2 papers, 2021 to 2025). A rare, genetically heterogeneous, primarily respiratory disorder characterized by chronic upper and lower respiratory tract disease. "Discovery of new disease genes—Four genes, i.e., TTC12, GAS2L2, DNAH9 and DNAJB13, whose mutations are responsible for Primary Ciliary Dyskinesia (PCD) have been identified through molecular and cellular studies performed in the framework of the RaDiCo-DCP cohort." (PMID 34715889, 2021). "The importance of this gene is further highlighted in Primary Ciliary Dyskinesia (PCD), an autosomal recessive ciliopathy, where DNAJB13 variants account for 12–18% of cases and cause similar defects in sperm tail structure and energy metabolism." (PMID 41413469, 2025).
colon cancer (1 paper, 2024). "The high expression of DNAJB13 in colon cancer tissues also confirmed that DNAJB13 is an independent prognostic risk factor for colon cancer patients." (PMID 39099656, 2024).
cryptorchidism (1 paper, 2014). The failure of one or both testes of a male fetus to descend from the abdomen into the scrotum during the late part of pregnancy. "In a previous study, we first reported that DNAJB13 was expressed abundantly in mouse testis and up-regulated in cryptorchidism." (PMID 25233908, 2014). "In a previous study, we cloned mouse Dnajb13, which is up-regulated in cryptorchidism." (PMID 25233908, 2014).
Hydrocephalus (1 paper, 2016). Hydrocephalus is an active distension of the ventricular system of the brain resulting from inadequate passage of CSF from its point of production within the cerebral ventricles to its point of absorption into the systemic circulation. "Not only was the lethal phenotype of hydrocephalus suppressed, but we also found that Dnajb13 is required for sperm cilia formation." (PMID 27530713, 2016).
tumor (2 papers, 2020 to 2021). "Of note, top genes with sex differences in expression within tumor tissues, namely ITPR3 and DNAJB13, show sex-dependent association with stage, which was replicated in TCGA series." (PMID 33527138, 2021). "The expression levels of DNAJB1, DNAJB5, DNAJB6, DNAJB11, DNAJB12, DNAJB13, and DNAJB14 were significantly upregulated in the tumor tissues." (PMID 32984053, 2020).
infection (1 paper, 2014). The state of being infected such as from the introduction of a foreign agent such as serum, vaccine, antigenic substance or organism. "For instance, Dnajb9L2, Dnajb11, Dnajb12b, Dnajc3, Dnajc20, Dnajc21, and Dnajc29 were up-regulated at only one time point (1.5× fold change cutoff); similarly, Dnajb13 was only down regulated at 24h after infection." (PMID 25542027, 2014).
DNAJB13 also shares sentences with these, for which no sentence is quoted: teratozoospermia (2 papers); ciliopathy (1); congenital generalized lipodystrophy (1); Frasier syndrome (1); Kallmann syndrome (1); liver cirrhosis (1); Neurodevelopmental delay (1); Noonan syndrome (1); prostate carcinoma (1).